ALDH3B1 (aldehyde dehydrogenase 3 family member B1)
Description:
Oxidizes medium and long chain saturated and unsaturated fatty aldehydes generated in the plasma membrane into non-toxic fatty acids. May have a protective role against the cytotoxicity induced by lipid peroxidation. Short-chain fatty aldehydes are not good substrates. Can use both NADP(+) and NAD(+) as electron acceptor in vitro, however in vivo preference will depend on their tissue levels. Low activity towards acetaldehyde and 3,4-dihydroxyphenylacetaldehyde. Able to metabolize aromatic aldehydes such as benzaldehyde to their acid form.
Synonyms: ALDH7; ALDH4
Tractability: Small molecule: it belongs to a druggable protein family. Antibody: UniProt places it where antibodies can reach, with high confidence; its Gene Ontology location is reachable by antibodies, with high confidence. PROTAC: ubiquitination databases record sites on it; its protein half-life has been measured.
Gene: Protein-coding gene on chromosome 11 (68,008,563 to 68,029,282, forward strand). Ensembl gene ENSG00000006534.
Subcellular location: Cell membrane
Pathways (Reactome):
Immune System: Neutrophil degranulation
Metabolism: Sphingolipid catabolism
Gene Ontology:
Molecular function: aldehyde dehydrogenase [NAD(P)+] activity; protein binding; 3-chloroallyl aldehyde dehydrogenase activity; aldehyde dehydrogenase (NAD+) activity; aldehyde dehydrogenase (NADP+) activity; benzaldehyde dehydrogenase (NAD+) activity; benzaldehyde dehydrogenase (NADP+) activity; long-chain fatty aldehyde dehydrogenase (NAD+) activity; medium-chain fatty aldehyde dehydrogenase (NAD+) activity; oxidoreductase activity; oxidoreductase activity, acting on the aldehyde or oxo group of donors, NAD or NADP as acceptor
Biological process: aldehyde catabolic process; cellular response to oxidative stress; response to oxidative stress; alcohol metabolic process; aldehyde metabolic process; lipid metabolic process; sphingolipid catabolic process; ethanol catabolic process
Cellular component: cytoplasm; extracellular exosome; vesicle; plasma membrane; secretory granule membrane; specific granule membrane; cytosol
Genetic constraint (gnomAD): Loss-of-function variants: 36 observed, 39.08 expected, observed/expected ratio (o/e) 0.92, 90% interval 0.7 to 1.22. The upper end of that interval is the gene's LOEUF score, 1.22, which puts it in group 5 of 6, group 1 being the genes least tolerant of losing a copy. Missense variants: 589 observed, 588.11 expected, observed/expected ratio (o/e) 1, 90% interval 0.94 to 1.07. Synonymous variants: 276 observed, 242.39 expected, observed/expected ratio (o/e) 1.14, 90% interval 1.03 to 1.26.
Homologues: Orthologues: chimpanzee ALDH3B1 (98% identical), rat Aldh3b1 (85% identical), guinea pig ALDH3B1 (84% identical), mouse Aldh3b1 (84% identical), zebrafish aldh3a2a (50% identical), zebrafish aldh3a2b (49% identical), zebrafish aldh3b4 (47% identical), Caenorhabditis elegans alh-4 (46% identical), tropical clawed frog aldh3b1 (46% identical), Caenorhabditis elegans alh-5 (43% identical), tropical clawed frog aldh16a1 (26% identical), Caenorhabditis elegans alh-3 (25% identical), and 5 more. Paralogues in human: ALDH3B2 (68% identical), ALDH3A2 (53% identical), ALDH3A1 (51% identical), ALDH1A3 (27% identical), ALDH1A2 (26% identical), ALDH1L2 (26% identical), ALDH1B1 (25% identical), ALDH1L1 (25% identical), ALDH2 (25% identical), ALDH9A1 (25% identical), ALDH1A1 (25% identical), ALDH8A1 (24% identical), and 5 more.